SOX2 (SRY-box transcription factor 2)
Diseases named in the same sentence as SOX2 in open-access papers (continued):
Sharing a sentence is not in itself a finding about the gene and the disease.
tumor (continued). "In order to verify the association of MCT1 expression and stemness properties in human PDAC tissue, consecutive sections of FFPE tumor tissues from PDAC patients (all with resectable T3N1M0 tumors) were immunostained with antibodies directed against MCT1, KLF4, and Sox2, respectively." (PMID 32138176, 2020). "We have to acknowledge that the LSD1/SOX2 axis may represent a provocative potential target for CSC elimination not only in luminal-B and HER2-positive tumor but also in the basal-like subtype, which can also be found in the SOX2-overexpressing IntClust5." (PMID 32191225, 2020). "Colocalization analysis revealed that 48% of ASCL1+ tumor cells were positive for the proliferation marker Ki67, whereas over 90% of ASCL1+ cells were OLIG2+ and SOX2+, indicating that these three transcription factors are coexpressed in the majority of the PDX‐GBM cells in vivo." (PMID 32573857, 2020). "Significantly, we have observed growth inhibition in every tumor cell line tested in this laboratory when SOX2 is elevated, including 7 additional tumor cell lines (data not shown) that we have not yet reported." (PMID 32998722, 2020). "The researchers speculated that the effects of the ESCM on tumour reversion may result from the exchange of materials between cells, thereby rebalancing the expression of the stemness factors OCT4, SOX2, KLF and c‐MYC in tumour cells." (PMID 32588948, 2020). "This distinction is underscored by experimental evidence indicating that various AKT or PI3K inhibitors, but not the mTORC1 selective inhibitor rapamycin, affect SOX2 protein homeostasis in several tumor entities." (PMID 31477842, 2020). "Since the duration of tumor IFNγ signaling and overexpression of ISG.RS accounted for the resistant to ICIs,20 21 we hypothesized that SOX2 impaired CD8+ T-cell killing through regulating the IFNγ signaling." (PMID 33158915, 2020). "From the fore mentioned results we can conclude that the upregulation of Sox2 may play an important oncogenic role in HCC and can be considered as an acquired malignant proliferative phenotypic feature of tumor cells." (PMID 33112555, 2020). "We and others have found that ovarian CSCs co-expressed Nanog, Sox2, and Oct4, whereas expression of these genes is reduced or absent in tumor non-CSCs." (PMID 32013179, 2020). "We identified tumor initial cells (TICs) from a number of ESCC cell lines and demonstrated increased expression of GASC1 in the ESCC ALDH + TICs and its involvement in TICs maintenance by specific demethylation of H3K9Me3 at the SOX2 and NOTCH1 promoter." (PMID 32411232, 2020). "Currently, the mechanisms through which elevated levels of SOX2 restrict tumor cell proliferation have not been characterized." (PMID 32998722, 2020). "Our finding that this occurs in many different tumor cell lines leads us to propose that elevating SOX2 inhibits the growth of tumor cells by activating a well-conserved mechanism, rather than using a different mechanism in each tumor type." (PMID 32998722, 2020). "Also, PTC cells with DOCK9-AS2 knockdown presented restrained tumor sphere forming efficiency and lowered levels of stemness-related proteins including CD133, Nanog, OCT4, SOX2, EpCAM, and ALDH1A1." (PMID 32917852, 2020). "A recent study elucidated the role of lung cancer lineage specifiers SOX2 and NKX2-1 in tumor cell fate and neutrophil recruitment, suggesting that the determination of tumor immune microenvironment might impact the nature of the tumor." (PMID 32351880, 2020). "We analysed the expression of OCT4, SOX2, CK14, CK18, and WNT1 in the tumour tissues." (PMID 32307830, 2020). "Among these cell lines, HT29 cell line was highly expressed with FBX8, SOX-2 and SOX-2, and CD44, while quite weakly expressed with CDK4, HIF-1α, and c-Myc, indicating that HT29 cell line was an appropriate model to study tumor dormancy." (PMID 32796813, 2020).
tumor (continued). "Six showed no SOX2 staining, two showed scattered positive cells and only two showed focal staining (<10% of tumor surface)." (PMID 32575483, 2020). "Our finding that the cell cycle distribution of four tumor cell lines exhibited little or no change when SOX2 was elevated raised the possibility that elevating SOX2 acts by altering the cell cycle machinery for all phases of the cell cycle." (PMID 32998722, 2020). "We performed tumor sphere formation assays using Caco-2 and HCT116 cells to enrich cells with CSC-like characteristics, and qPCR showed that expression of the stem cell markers SOX2, OCT4, Nanog and KLF4 was high in the tumor spheres." (PMID 31754405, 2019). "In addition, comparative qPCR analysis of the tumor samples showed that the combination treatment resulted in the lowest level of CDK6, β-catenin, Sox2 and lncSNHG15." (PMID 31462285, 2019). "PD‐L1 expression was also observed in Sox‐2‐negative (non‐tumor) cells; however, it was not present on tumor‐infiltrating CD3+ T cells." (PMID 31929892, 2019). "The resulting non-secreting tumours in our mouse models are composed predominantly of SOX2+ stem cells and display signs of squamous differentiation." (PMID 30912742, 2019). "Moreover, METTL3 or IGF2BP2 expression positively correlated with the SOX2 downstream genes CCND1, MYC, and POU5F1 in our independent cohort of paired CRC tumor and adjacent normal tissues from SYSUCC." (PMID 31230592, 2019). "On day 28, expression levels of Nanog, Sox2, and Oct4 in circulating GFP+ cells and cells injected into mammary fat pads (orthotopical (OT) injection) were similar, suggesting that static tumor cells acquire stemness property in the tumor microenvironment." (PMID 30651129, 2019). "SOX1 and SOX2 ELISA results were markedly concordant (>98%): one LEMS-SCLC patient and one non-tumour LEMS patient had positive SOX2 antibodies but negative SOX1 antibodies." (PMID 30445363, 2019). "In our study, the expression of SOX2 did not correlate to T classification, neck lymph node metastasis, disease stage, histological grade, tumor recurrence, and second primary carcinomas development." (PMID 31640140, 2019). "Particularly, pharmacological inhibition of ERK5 using XMD8-92 reduced the rate of primary and secondary sphere formation, the expression of pluripotency transcription factors SOX2, NANOG, and OCT4, and the proportion of tumor cells with increased ALDH activity." (PMID 30774996, 2019). "Similarly, in colorectal cancer cells, PrPc overexpression is accompanied by the upregulation of the stemness markers Oct4, Nanog, Sox2, and ALDH1A1, which is correlated with tumor growth, proliferation, and angiogenesis." (PMID 31618844, 2019). "Genetic linage tracing experiments in a mouse model of ACP showed that SOX2+ cells targeted with mutant β-catenin did not autonomously give rise to the tumor mass but instead generated the tumor from neighboring cells in a paracrine manner." (PMID 31708878, 2019). "Altogether, the Sox2+ population comprised diverse cell types including both normal glia and tumor-derived cells with either glial and neural progenitor-like characteristics." (PMID 31863004, 2019). "While those without adjuvant therapy had largely the same SOX2 expression in the recurrence as compared to the primary tumor." (PMID 31718604, 2019). "We aimed to establish if SOX2 antibodies could be used to identify SCLC and other tumours found in a range of paraneoplastic disorders and controls." (PMID 30445363, 2019). "Thus, modulation of OCT4 and SOX2 protein expression occur via differentiation signals, and MEIS1 is contributed in this modulation of tumor cell differentiation." (PMID 31090196, 2019). "In addition, a significantly higher expression of CSC-related genes (NANOG, OCT4, SOX2, KLF4) was found in spheroids formed from ascites-derived tumor cells, compared to monolayer cells by qPCR." (PMID 31212816, 2019).
tumor (continued). "Moreover, Western blot analysis demonstrated that AP-2α decreased the expression of Nanog, Sox2 and CD133, and increased the levels of GFAP in both U251 cells and subcutaneous mouse tumor tissues originating from U87 cells." (PMID 31534499, 2019). "We attempt to analyze the expression of SOX2 protein of primary HGG and its paired recurrent tumor in order to better understand the biological behaviour of HGG and the transformation law of SOX2 in primary and recurrent HGG, and eventually enrich our kownledge of HGG." (PMID 31718604, 2019). "Although previous research has shown that Sox2+ cells are more resistant to chemotherapy compared with Sox2− bulk tumor cells in SHH-MBs with wild-type p5321, the mechanism by which Sox2+ cells evade therapy remains unclear." (PMID 31763624, 2019). "BI 853520 treatment, however, did not alter tumor stem cell marker (SOX2, ALDH1, NANOG, c-myc, CD44, Oct4) expressions of human tumor spheroids formed by different MPM cell lines." (PMID 30539198, 2019). "In addition, the protein levels of TAZ and SOX2 in 12 paired freshly collected HNSCC and adjacent non-tumor epithelial were also detected by western blot." (PMID 31399556, 2019). "We analyzed the significance among normal and tumor tissues, and we found that only OCT4 (p value < 0.0001) and SOX2 (p value = 0.0014) had higher expression in tumor tissues, not so for KLF4 (p value = 0.0610), C-MYC (p value = 0.0900), or NANOG (p value = 0.0969)." (PMID 31885625, 2019). "For in vivo experiments, a xenograft model where OSCC cells stably expressing ADAR1 were implanted was used to investigate the effect of ADAR1 on tumor growth and progression, and the expression of ADAR1, PCNA, SOX2 and POU5F1 was further detected by immunohistochemistry." (PMID 31315644, 2019). "Interestingly, they inhibit the expression of OCT4/SOX2 or CD133 in human GBM cell line by targeting specifically their promoters, as well as decrease tumor growth both in vitro and in vivo, but fail to eradicate completely the tumor." (PMID 31752169, 2019). "Although the association of SOX2 and OCT4 expression with CSCs has been well established in diverse types of cancer, the role of these CSCs in tumor development remains to be elucidated due to the lack of specific inhibitors of CSCs." (PMID 31500347, 2019). "Our results suggested that downregulation of TLR5 in TNBC increased tumor invasiveness and EMT expression via TRAF6 and SOX2 pathway and TLR5 could serve as a prognostic and monitoring indicator for TLR5-positive tumors." (PMID 31852883, 2019). "Interestingly, the embryo/germ cell-related markers, such as Oct4, Sox2, Nanog, and SSEA123–26, are often used as markers for cancer stem cells (CSCs), which are believed to play a vital role in tumor initiation, progression, and metastasis." (PMID 30302273, 2018). "Moreover, the expression of CSC-related transcriptional factors, Nanog, Oct4 and Sox2, were enhanced by CXCL1 in SW620 tumor spheroids." (PMID 30115896, 2018). "Next, we assessed the expressions of the 12 lncRNA in 92 serum samples (46 NSCLCs and 46 healthy controls) and identified two lncRNA [SOX2 overlapping transcript (SOX2OT) and ANRIL] that were overexpressed in tumor serum samples compared with healthy controls (all at P < 0.01)." (PMID 29504701, 2018). "Additionally, we also checked the expression of stem cell markers (SOX2 and aldehyde dehydrogenase 1 family, member A1 (ALDH1A1)) in the tumor samples." (PMID 30150594, 2018). "Recently, the transcriptional network ZEB1/OLIG2/SOX2 has been shown to be crucial in GBM irrespective of driver mutations, playing an important role in tumor initiation, stemness properties, proliferation and tumorigenicity." (PMID 30158599, 2018).
tumor (continued). "Subsequently, PHF20 was found abundantly expressed in neurogenic tumors and plays a vital role in carcinogenesis by significantly up-regulating the expression of SOX2 and OCT4, further enhancing the self-renewal and tumor-initiating capability of neuroblastoma." (PMID 30619286, 2018). "Finally, the expression of stemness markers SOX2 and OCT-4 was increased as mRNA level in tumor enriched with ALDH1A1." (PMID 30541574, 2018). "Similarly, si-hVDAC1 treatment of A549-derived tumours greatly decreased the expression of ABCG2, SOX2, CD44, CD144, CD133, KLF4, Oct3/4, EPCAM and Nanog, also as evaluated by IHC, immunoblotting or q-RT-PCR." (PMID 30544833, 2018). "Similar to this, TIMP-1/Sox2 co-expressing cells were detected in some of the tumor biopsies and in the corresponding organotypic spheroids, although the majority of the Sox2+ cells did not co-express TIMP-1." (PMID 29523123, 2018). "TrkAIII transfectants also exhibit elevated expression of the NB tumour stem cell-markers CD117, SOX2, Nestin and Nanog, indicating that TrkAIII not only blocks NGF/TrkA-induced NB cell differentiation but also promotes a more NB tumour stem cell-like phenotype." (PMID 29914559, 2018). "Overall, SOX2 expression was not significantly correlated with gender, age or localization of the tumor." (PMID 29596469, 2018). "In representative tumor samples with high, low and absent SOX2 expression, SOX2 was negatively correlated with ki67." (PMID 29596469, 2018). "SOX2 is an epigenetic reprogramming factor and oncogene shown to regulate androgen-independent CRPC proliferation and evasion of apoptosis and to promote tumor metastasis by inducing EMT." (PMID 29888169, 2018). "To ensure that phosphorylation of Sox2 is not a cell-line specific phenomenon, we examined Sox2 phosphorylation in fresh primary BC tumor samples." (PMID 29401647, 2018). "while that of SOX2 was significantly upregulated (p = 0.0027) in tumor specimens compared to noncancer tissues." (PMID 29849920, 2018). "Furthermore, we adopted Western blotting to confirm the protein levels of Nanog, Sox2 and Oct4 in three RCC tumour spheres." (PMID 30246456, 2018). "We could collect Sox2+ living tumor cells by FACS sorting and examine several features specific to CSCs, including chemoresistance, asymmetric division, and in vivo tumor growth with relatively few tumor cells." (PMID 30518951, 2018). "In addition, CD133 depletion also suppresses tumor cell proliferation, colony formation, and the expression of stemness transcription factors including NANOG, OCT4, SOX2, and c-MYC." (PMID 29568348, 2018). "In this paper, we show that the expression of oncogenic β-catenin and activation of the WNT pathway in Hesx1+ embryonic pituitary precursors or Sox2+ pituitary stem cells in young mice results in the activation of a robust SASP in targeted cells and the subsequent paracrine formation of tumours." (PMID 29180744, 2017). "Immunohistochemical staining for OCT4, SOX2, and NANOG in OCSCC demonstrates that OCT4 and SOX2 are expressed significantly higher in tumor-adjacent tissue compared to both normal tissue and the tumor." (PMID 28626726, 2017). "It is evident from the studies where SOX2 was elevated from an inducible transgene that many, if not most, SOX2-expressing tumor cell lines are growth inhibited when SOX2 is suddenly elevated." (PMID 28388544, 2017). "Sox2+ stem/progenitor cells in the adult mouse pituitary further evinced tumour-inducing potential in a non-cell-autonomous manner." (PMID 29158570, 2017).
tumor (continued). "Furthermore, we observed a significantly lower level of H3K27me3 mark in Sox2, Ngfr and Krt5/6 loci compared to those in ADC tumours, consistent with de-repression of these squamous loci in SCC tumours." (PMID 28387316, 2017). "SOX2 exhibited high expression in the nucleus of the tumor cells, with its expression being negative in 29 cases (38.7%), weakly positive in 27 (36.0%) and strongly positive in 19 (25.3%)." (PMID 28262804, 2017). "We found that patients that presented with metastasis also presented higher levels of SOX2-positive tumor cells than patients that did not present with metastasis." (PMID 28934267, 2017). "This, in turn, would activate BTIC marker OCT3/4, a direct target of HIF-2 α, along with BTIC marker SOX2, and the critical pluripotent stem cell inducer–MYCC, an onco-protein whose increased expression plays a central role in multiple aspects of tumor cell biology." (PMID 28249000, 2017). "In contrast to Sox2, the Sox9+ cells were not concentrated next to certain areas of the tumour, but rather widely distributed among all the adjoining brain parenchyma." (PMID 29158570, 2017). "(SOX2 and Tumor-Initiating Cells/Cancer Stem Cells), this problem was avoided in those studies where GFP had been knocked into the endogenous SOX2 locus, and GFP+ cells were isolated and tested for enrichment of tumor-initiating/cancer stem cells." (PMID 28388544, 2017). "Expressions of SOX2, OCT4, WNT, NANOG, ABCG2 and ALDH1A1 was assessed both at transcriptional and translational levels from spheroids and sorted populations of CD44+/24− and ALDH+ cells of CT-TNBC tumor (CSC) versus the whole tumor." (PMID 28835684, 2017). "In these three studies, SOX2-positive cells exhibited a higher frequency of TIC compared to the SOX2-negative cells of the same tumor cell population in a limiting cell dilution tumor assay." (PMID 28388544, 2017). "Immunostaining against SOX2 showed lack of expression of this stem cell marker in the murine tumours." (PMID 29180744, 2017). "We observed that expressions of both SOX2 and ABCG2 were higher in mammospheres as compared to the adherent cells, indicating enhanced expression of the respective genes in the CSC compartment of human tumor tissues." (PMID 28835684, 2017). "To test whether decreased levels of SOX2 also block metastasis capability in vivo, we performed tail vein injection of ZR7530 and studied tumour seeding and development in the lung." (PMID 28288641, 2017). "The comparative analysis of immunofluorescence results obtained from particulartumours (G113, G114 and G116) cultured as three experimental models (10%adh, 0% sph, 0% adh) revealed the presence of selected CSCsmarkers (SOX2, nestin and CD44) in G113 and G116 tumour-derived cells." (PMID 28522553, 2017). "Moreover, it was also revealed that the repressive effect of miR-145 on tumour metastasis was mediated by inhibiting the epithelial-mesenchymal transdifferentiation (EMT) and metastastic ability, partially by regulating Oct4/Sox2/Fascin1." (PMID 29348831, 2017). "In addition, we also investigated the co-expression of Sox2 and Sox9 with the oligodendrocyte transcription factor 2 (Olig2) as well as the glial fibrillary acid protein (GFAP) to define tumour surrounding cerebral microenvironment." (PMID 29158570, 2017). "RT-PCR and densitometric quantification analysis was used to quantify mRNA expression of a panel of stemness genes (NANOG, OCT-4, SOX-2, KLF4 and C-MYC), in addition to the CSC-specific markers, CD133 and ALDH1, in a cohort of matched normal and tumor lung tissues from NSCLC patients (n=20)." (PMID 29069808, 2017). "Thus, the effect of elevating SOX2 in these tumor cell lines, in particular PDAC tumor growth, is growth inhibition." (PMID 28388544, 2017). "In addition, some critical markers of tumor stem cells such as OCT4 and SOX2 transfactors were stimulated." (PMID 28881812, 2017).